PRR14 (proline rich 14)
Diseases named in the same sentence as PRR14 in open-access papers:
PRR14 is named in the same sentence as 19 diseases in open-access papers, as found by Europe PMC text mining. Sharing a sentence is not in itself a finding about the gene and the disease. The quoted sentences say what the papers report.
lung carcinoma (5 papers, 2016 to 2024). "Aberrant expression of PRR14 is associated with the tumorigenesis and progression of lung cancer." (PMID 31596887, 2019). "Proline-rich protein 14 (PRR14) is a newly discovered gene that is significantly overexpressed in cancer tissue, including lung cancer and breast cancer, located in the 16p11.2 region." (PMID 38540680, 2024). "As a well-known oncogene, many studies have demonstrated the upregulation of PRR14 in breast cancer, lung cancer, colon cancer, and so on." (PMID 36247752, 2022). "Its role in tumorigenesis has been firstly identified in lung cancer, in which, PRR14 functions as an oncogene by activating the PI3K/AKT/mTOR signaling pathway." (PMID 32541902, 2020). "PRR14 is amplified and aberrantly overexpressed in lung cancer, and promotes lung cancer cells proliferation through the activation of the PI3K/AKT/mTOR signaling pathway." (PMID 31596887, 2019). "We assume activation of the signal pathway may be a common mechanism of PRR14’s function as oncogene in both lung cancer and breast cancer." (PMID 32541902, 2020).
breast carcinoma (4 papers, 2020 to 2024). "Furthermore, genetic analysis indicates that PRR14 is rarely mutated and the majority of genetic alterations in breast cancer are gene amplification, which imply that gene overexpression instead of pathogenic mutation has an important role in regulating PRR14’s function during breast tumorigenesis." (PMID 32541902, 2020). "Recent study had found that PRR14 overexpression was involved in breast cancer, and the cancer cell proliferation and tumor formation was promoted by its uprugulation." (PMID 37325059, 2023). "To confirm PRR14’s function as an oncogene in breast cancer in vivo, we perform xenograft experiments." (PMID 32541902, 2020). "In correspondence, CHEK2 and PRR14 show opposite impact on breast cancer patients receiving chemotherapy." (PMID 32541902, 2020). "Here, using an integrated approach consisting of bioinformatic analysis, in vitro and in vivo biochemistry studies, we explore PRR14’s function in breast cancer." (PMID 32541902, 2020). "Biochemical analysis reveals, in addition to previously reported activation of PI3-kinase/Akt/mTOR pathway, PRR14 overexpression regulates cell cycle in breast cancer by inhibiting CHEK2’s activation, followed with the deregulation of DNA damage pathway." (PMID 32541902, 2020). "This is consistent with the previous result that PRR14 activates the Akt/mTOR signaling pathway in breast cancer." (PMID 32541902, 2020). "We check the expression of CHEK2 and PRR14 in the tumors from our previous xenograft experiment and human breast cancer samples." (PMID 32541902, 2020). "Here in breast cancer, both differential expression analysis and in vitro biochemistry analysis show PRR14 strongly activates the signaling pathway as well." (PMID 32541902, 2020). "Using qRT-PCR analysis, the upregulated transcription of PRR14 in breast cancer is confirmed in 7 pairs of matched human breast cancerous and adjacent normal tissues (P = 0.040)." (PMID 32541902, 2020). "Among all the PRR14-overexpressing cancers, breast cancer shows the most significant increase of PRR1420." (PMID 32541902, 2020). "In light of the fact that transcriptome in breast cancer differs greatly among subtypes, PRR14’s transcription among different intrinsic molecular subtypes defined by PAM50 (Normal-like, Basal, LumA, LumB and Her2) is compared." (PMID 32541902, 2020). "Collectively, our study is the first to document the oncogenetic role of PRR14 in breast cancer, which protects cells from apoptosis and stimulates proliferation by activating the PI3-kinase/Akt/mTOR pathway and inhibiting the CHEK2 pathway." (PMID 32541902, 2020). "Nuclear envelope component PRR14 has been detected to be upregulated in varieties of cancers, especially in breast cancer." (PMID 32541902, 2020). "Both of these pathways are of great influence in breast cancer and PRR14 appears to be their novel interacting node, which renders patients more resistance to chemotherapy and provides a potential therapeutic target in breast cancer." (PMID 32541902, 2020). "Data mining from TCGA shows consistent copy number increase in this region, which positively correlates with PRR14 transcription in breast cancer (P = 0.001, R2 = 0.175)." (PMID 32541902, 2020). "Further, we measure PRR14’s expression by immunohistochemical staining of human breast cancer tissue microarray (TMA), which comprises normal breast tissue, invasive ductal carcinoma and invasive lobular carcinoma." (PMID 32541902, 2020). "As expected, the transcription of PRR14 in breast cancer, measured either by RNAseq or gene expression array, is significantly enhanced." (PMID 32541902, 2020). "Moreover, PRR14 has found to be high expressed in breast cancer, and promoted cell proliferation by activating PI3K/Akt/mTOR pathway." (PMID 37325059, 2023). "Increased PRR14 expression promotes breast cancer cell proliferation and tumor formation." (PMID 32541902, 2020).
breast carcinoma (continued). "Human breast cancer samples are classified into two groups according to PRR14’s protein level." (PMID 32541902, 2020). "To determine whether PRR14 has a functional role in breast cancer carcinogenesis, we employ two commonly used breast cancer cell lines, MCF7 and MDA-MB-231." (PMID 32541902, 2020). "Here we confirm PRR14 gene is amplified and overexpressed in breast cancer." (PMID 32541902, 2020). "Altogether, these results indicate that PRR14 promotes breast cancer tumorigenesis." (PMID 32541902, 2020). "As genotoxic reagents including Eto are involved in the chemotherapy of breast cancer, we check the influence of CHEK2 and PRR14 on patients’ response to chemotherapy." (PMID 32541902, 2020). "This indicates PRR14’s upregulation activates the AKT/mTOR signal pathway and vice versa in breast cancer cells." (PMID 32541902, 2020). "We notice that another critical signal pathway in breast cancer, ATM Signaling Network in Development and Disease (P = 0.000321, q = 0.0318), is also regulated by PRR14 in the result of the over-representation analysis." (PMID 32541902, 2020). "Our observation confirms PRR14’s overexpression and its effect on activating the PI3K/AKT/mTOR signaling pathway in breast cancer." (PMID 32541902, 2020). "In addition, PRR14 is newly found to regulate cell cycle by inhibiting tumor suppressor CHEK2, which further strengthens its function as an oncogene in breast cancer and confers cancer cell resistance to chemotherapy." (PMID 32541902, 2020). "Comparison between PRR14 genetically altered and unaltered breast cancer samples shows that CHEK2 transcription is reduced (P = 0.014) in PRR14 genetically altered breast cancer samples, accompanied by not significantly less protein and significantly less activated form p-CHEK2 (T68) (P = 0.038)." (PMID 32541902, 2020). "Therefore, we suspect PRR14’s function in breast cancer may not be limited to the activation of the PI3K/AKT/mTOR signaling pathway." (PMID 32541902, 2020).
colon cancer (3 papers, 2019 to 2023). "The table shows that PRR14 expression in colon cancer was strongly associated with tumor size (P = 0.012), distant metastasis (P = 0.045) and TNM stage (Tumor Node Metastasis stage) (P = 0.029), but not with the gender and age of the patients." (PMID 31596887, 2019). "SiRNA-mediated gene silencing of PRR14 inhibited colon cancer cell proliferation, cell cycle progression, migration and invasion." (PMID 31596887, 2019). "Functional study revealed that downregulation of PRR14 inhibited colon cancer cells growth, migration and invasion." (PMID 31596887, 2019). "PRR14 expression was associated with the malignant clinicopathological characteristics, including tumor size, distant metastasis and TNM stage of colon cancer." (PMID 31596887, 2019). "PRR14 plays an important role in the development and progression of colon cancer, and is a possible prognostic marker and therapeutic target for the disease." (PMID 31596887, 2019). "Colon cancer tissue microarray was used to analyze and compare the expression of PRR14 among some clinicopathological characteristics of colon cancer." (PMID 31596887, 2019). "To investigate the biological function of PRR14 in vitro, we knocked down PRR14 in two colon cancer cell lines–HCT116 and RKO–via siRNA-mediated gene silencing." (PMID 31596887, 2019). "The relationship between PRR14 expression levels and clinicopathological characteristics of colon cancer patients." (PMID 31596887, 2019). "In this study, we found that PRR14 was significantly upregulated in colon cancer, and this is consistent with the results of previous analysis of the TCGA database." (PMID 31596887, 2019). "PRR14 was highly expressed in colon cancer tissues, and the expression level was correlated with tumor size, distant metastasis and Tumor Node Metastasis stages." (PMID 31596887, 2019). "The expression of PRR14 in a variety of tumors in the TCGA database has also been analyzed, and it has been found that PRR14 is commonly elevated in a variety of tumors, including colon cancer." (PMID 31596887, 2019). "Also, PRR14 was overexpressed in colorectal cancer, and functional studies shown that PRR14 suppression can inhibit the proliferation, migration and invasion of colon cancer cells though Akt signaling pathway." (PMID 37325059, 2023). "PRR14 may promote the progression and metastasis of colon cancer, and may be a novel prognostic and therapeutic marker for the disease." (PMID 31596887, 2019). "This suggests that PRR14 may interact with other unknown molecules in regulating colon cancer development and progression, and the identification of these molecules is our next research direction." (PMID 31596887, 2019). "We analyzed the effect of PRR14 on colon cancer cell growth using the CCK8 assay." (PMID 31596887, 2019). "Apart from acting on the PI3K pathway through GRB2, whether PRR14 has another mechanism through which it regulates the development and progression of colon cancer, remains to be determined." (PMID 31596887, 2019). "Firstly, we used the GEPIA database to investigate the expression pattern of PRR14 in colon cancer." (PMID 31596887, 2019). "This suggest a role of PRR14 in the migration and invasion of colon cancer." (PMID 31596887, 2019). "Since the cytoskeleton enhances pseudopodia formation during the motility of cancer cells, and PRR14 was found to regulate cytoskeletal remodeling, it could be stated that PRR14 promotes the metastasis of colon cancer cells by modulating the structure of the cytoskeleton." (PMID 31596887, 2019). "In this study, we have investigated the possible role of PRR14 in colon cancer, by which we explored PRR14 expression in colon cancer, and studied the effects of its knockdown on the proliferation, migration and invasion of colon cancer cells, as well the formation of pseudopodia." (PMID 31596887, 2019). "To date, the role of PRR14 in colon cancer has not been reported." (PMID 31596887, 2019).
non-small cell lung carcinoma (2 papers, 2019 to 2023). A group of at least three distinct histological types of lung cancer, including non-small cell squamous cell carcinoma, adenocarcinoma, and large cell carcinoma. "Besides, it has been reported that PRR14 can be used as an independent prognostic marker and may be a potential therapeutic target in the treatment of non-small cell lung cancer (NSCLC)." (PMID 31596887, 2019). "It has been reported that PRR14 was abnormally overexpressed in the tumor tissues of patients with non-small cell lung cancer (NSCLC), and related to poor prognosis, and PRR14 overexpression promoted the proliferation of cancer cells." (PMID 37325059, 2023).
Parkinson disease (2 papers, 2021 to 2022). A progressive degenerative disorder of the central nervous system characterized by loss of dopamine producing neurons in the substantia nigra and the presence of Lewy bodies in the substantia nigra and locus coeruleus. "The nuclear envelope component proline-rich protein 14 (PRR14) is involved in the nuclear morphological alteration and activation of the mTOR (mammalian target of rapamycin) signaling pathway, and has been repeatedly shown to be upregulated in patients with Parkinson’s disease (PD)." (PMID 33001354, 2021).
breast tumor (1 paper, 2020). "In the rest 95 PRR14-positive samples, both the maximal immunoreactivity and the percentage of stronger immunoreactivity of PRR14 in breast tumor are higher than those in normal tissue." (PMID 32541902, 2020).
cognitive decline (1 paper, 2025). "SNPs in this region mapped to PRR14, SRCAP, and BCL7C—genes linked to brain function, neurodegeneration, and cognitive decline." (PMID 40332088, 2025).
Cognitive impairment (1 paper, 2022). Abnormal cognition is characterized by deficits in thinking, reasoning, or remembering. "As for the subgroup analysis, we first found that lower PRR14 levels were associated with severer cognitive impairments (P = 0.048)." (PMID 36247752, 2022). "Furthermore, decreased PRR14 was associated with severer cognitive impairments, and increased VCAM-1 was linked with severer PD and later AAO." (PMID 36247752, 2022). "Among patients with PD, decreased PRR14 and increased VCAM-1 were associated with severer cognitive impairments and severer PD (H&Y), respectively." (PMID 36247752, 2022). "Further explorations are required to fully understand the increased PRR14 effect on cognitive impairments during PD." (PMID 36247752, 2022). "Furthermore, we found that decreased PRR14 and increased VCAM-1 were linked with severer cognitive impairments and severer PD (H&Y), respectively." (PMID 36247752, 2022). "For two groups (with or without cognitive impairment) based on the MMSE test score and the level of education, it proved that lower serum PRR14 levels were linked with severer cognitive impairments (P = 0.048)." (PMID 36247752, 2022).
Constipation (1 paper, 2021). Infrequent or difficult evacuation of feces. "In addition, serum PRR14 level was found to correlate with constipation in PD patients." (PMID 33001354, 2021).
invasive ductal carcinoma (1 paper, 2020). "When compared among graded invasive ductal carcinoma, a higher percentage of stronger immunoreactivity of PRR14 is observed in higher grade." (PMID 32541902, 2020).
cancer (7 papers, 2016 to 2024). A tumor composed of atypical neoplastic, often pleomorphic cells that invade other tissues. "Next, we created a quadruple PRR14 mutant bearing four cancer-associated missense mutations that ablate the [S/T]P consensus sites (P243L, T267L, T270A and S277P)." (PMID 32317397, 2020). "Interestingly, PRR14 has been implicated in the development of tumors and cancers." (PMID 31596887, 2019). "In order to explore PRR14 expression in human cSCC tissues, a total of 33 cases of fresh tumor tissues and para-carcinoma normal tissues were collected to investigate the PRR14 expression in cSCC patients using RT-qPCR and Western blot." (PMID 37325059, 2023). "Specifically, we analyzed the role of five lncRNAs (BBC3, STK11IP, XIST, FDFT1, and PRR14), which are known to be related to cell growth and apoptosis in cancer development." (PMID 34295808, 2021). "Although the expression of PRR14 is upregulated in various types of cancers, the upregulation is most significant in breast cancer." (PMID 32541902, 2020). "The evidence of PRR14 overexpression activating the PI3K/AKT/mTOR signaling pathway in other types of cancer is needed." (PMID 32541902, 2020). "The data showed that the mRNA expression of PRR14 was higher in the cancer tissues than in the normal tissues." (PMID 31596887, 2019). "This implies PRR14 overexpression may be a common mechanism contributing to the PI3K/AKT/mTOR signaling pathway dysregulation in various types of cancer." (PMID 32541902, 2020). "PRR14 has found to be a novel biomarker for some human cancers 15-17, but there is no report in human cSCC." (PMID 37325059, 2023). "PRR14 positive signal was mainly detected in the nucleus of non-neoplastic epithelium cells and tumor cells, and PRR14 staining was obviously stronger in the cancer tissues than in the adjacent normal tissues." (PMID 31596887, 2019). "The results showed that, there were 62% (31/50) moderate or strong PRR14 staining in cSCC tissues, 38% (19/50) weak or non-staining, and negative staining in para-carcinoma normal tissues, indicated that PRR14 expression was higher in tumor tissues than in para-carcinoma tissues." (PMID 37325059, 2023).
tumor (4 papers, 2016 to 2023). "Another study had pointed out that PRR14 was also high expressed in colorectal carcinoma, and its overexpression was related to tumor size and lymph node metastasis." (PMID 37325059, 2023). "Overexpression of PRR14 in cSCC patients was reported firstly in this study and its high expression was related to differentiation, thickness and tumor node metastasis (TNM) stage of cSCC." (PMID 37325059, 2023). "We first found that PRR14 expression was overexpressed in tumor tissues from cSCC patients in this study, and found that its overexpression was related to clinicopathological factors including tumor thickness, TNM stage and differentiation." (PMID 37325059, 2023). "The result shows that less PRR14 expression derived from short hairpin RNA leads to significantly reduced tumor formation in mice." (PMID 32541902, 2020). "Pearson's correlation analysis showed that, high expression of PRR14 was related to clinicopathological factors of cSCC patients, the significant differences were found between positive PRR14 expression with tumor thickness (P=0.036), TNM stage (P=0.040) or differentiation (P=0.024)." (PMID 37325059, 2023). "The data from oncomine database also demonstrated a higher expression of PRR14 in tumor tissues." (PMID 31596887, 2019). "PRR14 expression was significantly correlated with tumor grade." (PMID 31596887, 2019).
neurodegenerative disease (1 paper, 2021). A disorder of the central nervous system characterized by gradual and progressive loss of neural tissue and neurologic function. "First, the sample size is rather small and serum PRR14 is not detected in other neurodegenerative diseases." (PMID 33001354, 2021).
PRR14 also shares sentences with these, for which no sentence is quoted: colorectal cancer (1 paper); cutaneous squamous cell carcinoma (1); invasive lobular carcinoma (1); laminopathies (1); lung adenocarcinoma (1); lung squamous cell carcinoma (1).